TNF (tumor necrosis factor)
Diseases named in the same sentence as TNF in open-access papers (continued):
Sharing a sentence is not in itself a finding about the gene and the disease.
Arthritis (continued). "Studies involving these demonstrated the crucial role of osteoclasts in the pathogenesis of articular bone erosion in arthritis induced by adjuvant, antigen, collagen, serum transfer and TNF." (PMID 26634933, 2016). "Mast cells play an essential role in some animal models of arthritis and are an important synovial reservoir of pro-inflammatory cytokines, including TNFα and IL-17, in RA." (PMID 27036513, 2016). "AIA in the rat and G6PI-induced arthritis in the mouse are both T cell-dependent arthritis models that require TNF and IL-6 for arthritis development." (PMID 27340371, 2016). "TNF-α is a pro-inflammatory cytokine that plays crucial role in the pathogenesis of several forms of arthritis, and, as a consequence, it represents a therapeutic target in such diseases." (PMID 27123929, 2016). "Cartilage degradation in arthritis is recognized to be induced by inflammatory cytokines, such as interleukin (IL)-6, IL-1β, and tumor necrosis factor-α (TNF-α)." (PMID 27411719, 2016). "In a study by our group using the CIA mouse model of RA, anti-TNF therapy ameliorated arthritis by decreasing numbers of Th1 and Th17 cells in arthritic joints, but also caused an increase in Th1 and Th17 cells in draining lymph nodes." (PMID 28010726, 2016). "We have also shown that PAD4 is important for TNF-α-driven lung inflammation in agreement with previous findings that PAD4 contributes to TNF-α-driven joint inflammation." (PMID 27450561, 2016). "A recent study found that in addition to acting as a major driver of bone destruction in arthritis, TNF-α can also upregulate the Wnt antagonist dickkopf-1 (Dkk-1) in FLSs, thereby inhibiting new bone formation in RA patients." (PMID 26821827, 2016). "Effects of sSiglec-9 were evaluated using a physiologic arthritis score, histological analysis, serum tumor necrosis factor (TNF)-α concentration, and the proportion of forkhead box P3 (Foxp3)-positive regulatory T (Treg) cells." (PMID 27267914, 2016). "The upregulation of HO-1 has been shown to inhibit local osteoclastogenesis in TNF transgenic mice with arthritis." (PMID 27314037, 2016). "His arthritis had been in remission on etanercept and previous open label trials suggest the efficacy of TNF-blocking therapy in Still's disease." (PMID 27818826, 2016). "PDAPEI/pDNA can significantly inhibit TNF-α expression in vitro and proved to have an excellent efficacy in decreasing the severity of arthritis in mice with CIA." (PMID 27594856, 2016). "MTX and N-f-5HT reduced the arthritis-increased transcription of TNF-α and iNOS in the liver to a comparable extent." (PMID 27556049, 2016). "Proinflammatory mediators such as TNF-α and IL-1 play significant roles in the pathophysiology of arthritis." (PMID 27881135, 2016). "Unexpectedly, studies in murine and human arthritis have indicated that anti-TNF treatment can increase circulating T helper 17 (Th17) cells, but the relationship to treatment response is unclear." (PMID 28010726, 2016). "H&E-stained ankle joint sections from mice that overexpress TNF-α only in the lungs were assessed for arthritis." (PMID 27450561, 2016). "Transfer of IL-17-deficient donor bone marrow into CIA DBA/1J mice inhibits development and severity of clinical arthritis, due to reduction in the secretion of the pro-inflammatory cytokines TNF-α, IL-1β and IL-6." (PMID 26634933, 2016). "As mentioned, in the K/BxN STA model, IL-1 is absolutely required for arthritis development, and TNF appears to play an important, but partial, role in the disease pathogenesis." (PMID 27313578, 2016). "In LVSmad7-injected joints, there were lower arthritis and histological scores with less synovitis, synovial hyperplasia and erosion on cartilage and bone as well as reduced IL-17 and TNF expression levels in comparison with other control groups." (PMID 27731365, 2016). "In the present study, we demonstrated that plasma levels of IL-1β and TNF-α correlated with ED throughout the arthritis course." (PMID 26761790, 2016).
Arthritis (continued). "All these factors have been demonstrated through the widespread clinical use of TNF-α-neutralizing agents to treat RA patients to improve arthritis and inhibit bone destruction." (PMID 26821827, 2016). "TNF-α directly affects joint degeneration and destruction in arthritis, and induces a cascade of other pro-inflammatory cytokines and proteins such as interleukins, prostaglandins, and angiotensin II in peripheral organs." (PMID 27833798, 2016). "For example, the absence of TTP in knockout mice leads to marked increases in tumor necrosis factor-α (TNFα) mRNA, which provokes a severe autoimmune disease marked by runting, cachexia, arthritis, and dermatitis." (PMID 27825143, 2016). "Triggering of arthritis by intra-articular injection of mBSA on day 21 of AIA induces not only arthritis but also a burst of proinflammatory cytokines including IL-12, IL-17 and TNF." (PMID 26512984, 2015). "For example, gold-containing therapeutics, TNF-α inhibitors, and methotrexate, all regularly used for treating arthritis, can effect NF-κB function." (PMID 25879437, 2015). "In the K/BxN moldel, fullerenes attenuated arthritis, an effect accompanied by reduced histologic inflammation, cartilage/bone erosion, and serum levels of TNF-α." (PMID 25879437, 2015). "In contrast, the TNFα-transgenic arthritis mouse model showed a primarily catabolic bone remodelling profile, while genes representing the osteoproliferative response showed no or marginally differential expression." (PMID 25889670, 2015). "To date, there have been few longitudinal studies that have evaluated the predictive role of IGRA in arthritis patients before anti-TNF therapy." (PMID 25746854, 2015). "The disease-modifying effects of green tea extract on arthritis in a collagen-induced arthritis (CIA) murine model was associated with reduced inflammatory mediators including COX-2, IFN-γ and TNF-α in arthritic joints." (PMID 26379475, 2015). "In a previous study, we reported a comparison of TST and the QFT assay for LTBI screening in 107 Korean arthritis patients before initiating anti-TNF treatment." (PMID 25746854, 2015). "PGRN-deficient mice were more susceptible to collagen-induced arthritis, and administration of PGRN reversed inflammatory arthritis through the inhibition of TNF-α signaling." (PMID 26696755, 2015). "Among the cytokines with the greatest importance in inflammatory responses, pain and arthritis, we selected nine cytokines for further study (IFNγ, TNFα, IL1, IL4, IL6, IL10, IL12, IL17 and IL23)." (PMID 26218592, 2015). "In Ttp-knockout mice, many inflammation syndromes such as dermatitis, cachexia, spontaneous arthritis, and neutrophilia are observed because of overproduction of the pro-inflammatory cytokine tumor necrosis factor-α (Tnfα) through its prolonged mRNA half-life." (PMID 26180518, 2015). "Several approaches to understanding the nature of poor anti-TNF response have been proposed, where genetic variations and TNF-independent mechanisms of arthritis have been extensively explored." (PMID 26420684, 2015). "The arthritis in pristane-treated mice also is likely to be TNFα mediated as it is ameliorated by TNF inhibitor therapy." (PMID 26097482, 2015). "TNF-α is directly involved in the pathogenesis of arthritis sustaining joint inflammation and cartilage destruction." (PMID 25793532, 2015). "Transgenic mice over-expressing TNF (TNF-Tg mice) develop a form of arthritis that is very similar to human RA." (PMID 26287732, 2015). "Corroborating our results, Yudoh and collaborators demonstrated that the water-soluble fullerene (C60) reduced the levels of inflammatory cytokines such as TNF-α in a rat model of arthritis." (PMID 25875016, 2015). "By using a specific LMP7 inhibitor in vivo, it was possible to suppress arthritis with production of pro-inflammatory cytokines such as TNF-alpha and IL-23, opening new possibilities for the treatment of autoimmune diseases." (PMID 25889472, 2015).
Arthritis (continued). "Overexpression of ADAMTS-7 accelerated the degradation of COMP and the onset and progression of arthritis through formation of a positive feedback loop with TNF-α." (PMID 26696755, 2015). "Apremilast has previously been shown to inhibit TNF-α production from human rheumatoid synovial cells and this ameliorates arthritis in the experimental model of collagen-induced arthritis." (PMID 26370839, 2015). "A TNF-α-specific antibody attenuated the symptoms of spontaneously developed arthritis in human TNF-α transgenic mice." (PMID 26213566, 2015). "The results revealed that acarbose at the dose of 500 mg/kg/day attenuated the incidence and severity of arthritis and the expression of proinflammatory cytokines, including TNF-α, IL-6 and IL-17 in the paw tissues." (PMID 26678745, 2015). "In the previous studies, TNF-α has been reported to play a crucial role in cartilage destruction in arthritis." (PMID 25653475, 2015). "This study evaluated the effectiveness of the QuantiFERON-TB Gold In-Tube (QFT) assay for diagnosing LTBI in arthritis patients undergoing anti-TNF treatment." (PMID 25746854, 2015). "Investigation of LTBI in arthritis patients who received anti-TNF treatment is very important because such patients are at increased risk of LTBI reactivation." (PMID 25746854, 2015). "In this context, a strategy based on QFT-G results, regardless of TST results, seems effective to safely prevent TB in arthritis patients undergoing anti-TNF treatment." (PMID 26294972, 2015). "Ameliorative efficacy of TSE was evaluated on arthritis induced inflammation quantitatively by determining the serum levels of TNF-α, IL-1β, IL-6 and IL-10 using ELISA kits." (PMID 26059174, 2015). "Several BMP ligands, including BMP2, BMP6, and BMP7, have been shown to be upregulated in the synovium of patients with RA as well as in tumor necrosis factor-alpha (TNF-α) transgenic mice developing arthritis and in collagen-induced arthritis models." (PMID 26215036, 2015). "Concurrent JAK + SYK inhibition resulted in higher efficacy than single kinase inhibition and TNF blockade in a chronic and severe arthritis model." (PMID 26653844, 2015). "The present study demonstrated that γ-tocotrienols are an effective inhibitor of arthritis-induced oxidative stress and TNF-α secretion." (PMID 24940448, 2014). "Although the disease window in this model is good, and statistically significant reductions in arthritis scores were attained with TNFα blockade, there was still some variability in the control responses." (PMID 25344414, 2014). "Because the pattern of effects of IL-1β on sensory neurons of the joint (opposite effects on C- and Aδ-fibers) is different to that of TNF-α and IL-6, it is an intriguing question how neutralization of IL-1β affects pain in arthritis." (PMID 25606597, 2014). "The main features of the model are that it is induced, that disease incidence appears to be close to 100%, arthritis scores can reach the maximal level and the model is responsive to TNFα blockade, even when the disease is well-established." (PMID 25344414, 2014). "The γ-tocotrienol treatment increased the antioxidant enzyme levels and decreased the TNF-α levels observed in arthritic rats, which provided protection against arthritis-induced joint damage." (PMID 24940448, 2014). "Early diagnosis is important, because new drugs such as antitumor necrosis factor (TNF) agents are effective on reducing disease progression, enthesitis, spinal mobility and arthritis." (PMID 24910782, 2014). "The experimental results show that both the CsA and the glycyrol treatments reduced the mean arthritis scores, and reduced the contents of IL-1β, TNF-α, IL-6, and IL-17 in the serum." (PMID 25036817, 2014). "Ling and Jamali (2009) first demonstrated the potential for TNFα DDDI using infliximab in a rat preadjuvant arthritis model." (PMID 24707356, 2014).
Arthritis (continued). "In vitro, immune complexes can stimulate MyD88−/− macrophages to produce TNFα, supporting the possibility that FcγR contribute to arthritis in MyD88−/− mice." (PMID 24967215, 2014). "Asarum extract was found to significantly reduce the severity of arthritis by decreasing hind paw swelling, the arthritis index, the spleen index, and TNF-α, IL-1β and IL-6 expression levels in plasma." (PMID 25289073, 2014). "C60 also suppressed the tumor necrosis factor alpha (TNF-α) induced production of proinflammatory cytokines in vitro and inhibited the arthritis in vivo." (PMID 24949448, 2014). "Although a role for IL-1 and TNF-α in the pathogenesis of arthritis has been suggested, the role of pro-inflammatory cytokines in the progression of PTA has not been elucidated." (PMID 24964765, 2014). "These authors showed that drugs which neutralize the action of TNF-α promoted reduction of pain and inflammation in rats with adjuvant-induced arthritis." (PMID 24971313, 2014). "Treatment with γ-tocotrienol to arthritis rats resulted in a significant reduction in TNF-α when compared with the untreated arthritis group (P<0.05)." (PMID 24940448, 2014). "The salient features of three of the key pro-inflammatory cytokines (TNFα, IL-6, and IL-17) involved in arthritis are summarized below." (PMID 25561237, 2014). "Some studies showed that somatostatin stimulates the production of IL-1β, TNF-α, and/or IL-6 by human blood cells, as well as the expression of IL-1β in articular tissues of rats with ongoing adjuvant-induced arthritis." (PMID 25530957, 2014). "Animals were assessed for arthritis symptoms using a clinical score, cytokine levels (human TNFα, IL-1β and IL-6) in sera and joints, and histopathology." (PMID 25344414, 2014). "Proinflammatory cytokines such as interleukin 6 (IL-6), tumor necrosis factor α (TNF-α) and IL-1β are critical mediators in the inflammatory process of arthritis." (PMID 24886976, 2014). "Arthritis patients on MTX or anti-TNF combined with MTX had a lower immune response compared to responses reported for healthy adults but still met CHMP serologic criteria for protection against infection." (PMID 24383620, 2014). "Accordingly, arthritis of the limbs was strongly induced by type ΙΙ collagen cocktail in CRY knockout mice, and this arthritis was suppressed by anti-TNF-α antibodies." (PMID 24901009, 2014). "The present study demonstrated that γ-tocotrienol supplementation in arthritic conditions attenuated the arthritis-induced elevation of the TNF-α level." (PMID 24940448, 2014). "It resulted in significant reduction in the severity of arthritis as well as TNFα mRNA level in the joints." (PMID 25561237, 2014). "Rats with FCA-induced arthritis had significantly (P<0.01) increased IL-1β, IL-6 and TNF-α expression levels compared with those in the normal control group." (PMID 25289073, 2014). "In the mouse collagen induced arthritis model, IL-17 effect was dependent on the presence of TNFα at the early phase, whereas at a later stage the disease was mostly IL-17 driven, which is TNFα independent." (PMID 25436214, 2014). "Assuming that there is a role for TNF-α in crystal induced arthritis, we have treated with infliximab two cases of severe CPDD resistant to NSAIDs treatment." (PMID 25436167, 2014). "In the same study, SB203580 also inhibited the circulating concentration of both IL-6 and TNFα in rat and mice with experimentally induced arthritis." (PMID 24995301, 2014). "Recent studies show that MDL-1 is highly expressed on TNF-activated monocytes and acts as a key regulator of synovitis and bone erosion in murine arthritis." (PMID 24465901, 2014). "There is substantial evidence demonstrating the importance of TNF-alpha in the inflammatory process of RA, and this cytokine is better value to assess the degree of the arthritis and also good targets for treating the disease." (PMID 25059987, 2014).
Arthritis (continued). "TNF-α is produced by macrophages and the synovial lining, and is present at higher concentration in individuals suffering from arthritis; TNF-α modulates the secretion of proinflammatory cytokines (IL-1 and IL-6) within the synovial joints." (PMID 24940448, 2014). "In a recent study N. sativa had increased both the IL-10 and TNFα concentration in normal rats, but in another study thymoquinone (N. sativa’s major bioactive component) reduced TNFα and increased IL-10 in the rat’s arthritis model." (PMID 25380621, 2014). "In AA model, Mtb induces destructive arthritis through the interaction with immune cells by the abundant release of inflammatory factors (tumor necrosis factor α, INF-γ, interleukin 1, and interleukin 6)." (PMID 25548591, 2014). "Although the exact molecular mechanisms responsible for cartilage and bone destruction have not been elucidated, studies have shown that pro-inflammatory cytokines TNF-α, IL-1β, and IL-6 play a critical role in the pathological process of arthritis." (PMID 25276195, 2014). "Available clinical data also support this concept (for example, the rapid reduction of mechanical hyperalgesia by neutralization of TNF-α in animal models of arthritis and in RA patients)." (PMID 25606597, 2014). "Cyp3a downregulation in a different, preadjuvant model of arthritis was inhibited by the anti-TNFα biologic infliximab." (PMID 24707356, 2014). "The untreated arthritis group showed a significantly higher concentration of TNF-α compared with the γ-tocotrienol-treated group (P<0.05)." (PMID 24940448, 2014). "When CG is accompanied by a major immune-mediated disease, such as inflammatory bowel disease or arthritis, it is reasonable to consider an anti-TNFα therapy that will control the major disease and improve and/or heal CG." (PMID 25433368, 2014). "The degree of toe swelling, arthritis index, spleen index, and the expression levels of tumor necrosis factor (TNF)-α, interleukin (IL)-1β and IL-6 were measured." (PMID 25289073, 2014). "In this case, TNF blockade (P = 0.0035), F8-huIL10 (P = 0.0561) and the combination treatment (P = 0.0023) inhibited arthritis progression upon day 8 when compared with saline." (PMID 24289726, 2013). "Under certain conditions, such as treatment with anti-arthritis drugs e.g. Adalimumab, Etanercept or Infliximab, that are based on neutralization of TNF-α or its receptor, the dormant Mtb becomes metabolically active, resulting in active TB." (PMID 23308269, 2013). "Yin and colleagues found that endostatin gene expression inhibited the development of arthritis, an inflammatory angiogenic disease, in TNF-transgenic mice." (PMID 23688086, 2013). "It represents a unique animal model for studying the molecular mechanisms of arthritis, especially the early phases of disease genesis and tissue remodeling steps upon abrogation of TNFα expression." (PMID 23740547, 2013). "Collagen-induced arthritic mice receiving siRNA targeting TNF-α via this systemic wraposome delivery exhibited significant decreases in the severity of arthritis coupled with reduction of TNF-α in the joints." (PMID 24276020, 2013). "Genetic ablation of TTP in mice causes arthritis that can be rescued by treatment with a TNF-α neutralizing antibody, demonstrating the major role of TNF-α." (PMID 23468959, 2013). "It reduced the severity of arthritis, primarily by reducing cartilage destruction, decreasing IL-6 and TNF-α production and reducing antigen-induced proliferation." (PMID 23349985, 2013). "Participants said they were often given information about anti-TNF while they were having a severe flare-up of their arthritis." (PMID 23663548, 2013). "Curcumin treatment downregulated clinical arthritis score, proliferation of splenic T cells, expression of TNF-α and IL-1β in the ankle joint, and serum IgG2a levels." (PMID 23476694, 2013).